SEMA3E (semaphorin 3E)
Diseases named in the same sentence as SEMA3E in open-access papers (continued):
Sharing a sentence is not in itself a finding about the gene and the disease.
atherosclerosis (5 papers, 2021 to 2025). A disease characterized by the build-up of fatty material and calcium deposition in the arterial wall resulting in partial or complete occlusion of the arterial lumen. "Interestingly, serum Sema3E levels are increased in patients with atherosclerosis who are at clinical risk for adverse cardiovascular events, potentially suggesting that Sema3E represents a biomarker for vascular inflammation." (PMID 33511463, 2021). "In contrast, the Sema3E–Plexin-D1 signaling axis inhibits the proliferation and migration of vascular smooth muscle cells (VSMCs), which are hallmarks of atherosclerosis and restenosis." (PMID 35045890, 2022). "During atherosclerosis regression, the expression of Sema3E in plaque macrophages was markedly suppressed, in conjunction with the reduced and enhanced expression of Nos2 and Arg1, respectively." (PMID 35045890, 2022). "The Sema3E–Plexin-D1 signaling axis promotes the development of atherosclerosis via the retention of inflammatory macrophages in the plaque." (PMID 35045890, 2022). "In contrast, semaphorin 3E (Sema3E) expression is increased in atherosclerotic plaque macrophages, and this effect is reversible when the lesions are moved to an atherosclerosis-regressive microenvironment." (PMID 33511463, 2021). "Thus, during the early stage of atherosclerosis, neointimal hyperplasia is promoted by a reduction in signalling through the SEMA3E‐PLXND1 axis, while during the late stage of atherosclerosis, the directional migration of macrophages is inhibited by the SEMA3E‐PLXND1 signalling axis." (PMID 33837646, 2021).
Obesity (5 papers, 2017 to 2022). Accumulation of substantial excess body fat. "Overall, the Sema3E–Plexin-D1 signaling axis is a promising therapeutic target for diet-induced obesity." (PMID 35045890, 2022). "Sema3E and its receptor PlexinD1 were upregulated in the adipose tissue of a dietary obesity mouse model." (PMID 32781674, 2020). "Infiltration of mononuclear-like cells and formation of crown-like structures in epididymal visceral WAT (eWAT) were note in mice with dietary obesity, while such changes were ameliorated by administration of Sema3E vaccine." (PMID 30846754, 2019). "This study was performed to develop a peptide vaccine for Sema3E and test its therapeutic potential in a murine model of dietary obesity." (PMID 30846754, 2019). "The Sema3E antibody titer was analyzed by ELISA, and the biological effects of the peptides were tested in mice with dietary obesity." (PMID 30846754, 2019). "Therefore, we further characterized the biological effects of the KLH-conjugated HKEGPEYHWS peptide (Sema3E vaccine) in mice with dietary obesity." (PMID 30846754, 2019). "Accordingly, inhibition of the Sema3E-Plexin D1 axis by vaccination may potentially be developed as a treatment for unhealthy obesity and diabetes." (PMID 30846754, 2019). "Therefore, we tested the effects of Sema3E vaccine on systemic metabolism in mice with dietary obesity." (PMID 30846754, 2019). "Taken together, these results suggest that a peptide vaccine targeting Sema3E could potentially become a therapeutic option for diabetes and/or unhealthy obesity in the future." (PMID 30846754, 2019). "Generation of an antibody directed against secreted Sema3E might be a promising approach, but considering the huge population of patients with unhealthy obesity and/or diabetes, we considered it crucial to develop a therapy that was also reasonable in terms of medical economy." (PMID 30846754, 2019). "In addition to mice with dietary obesity, the circulating Sema3E level is also increased in patients with diabetes, suggesting that suppression of this secreted molecule could become a next generation therapy for diabetes by inhibiting chronic inflammation in visceral WAT4." (PMID 30846754, 2019). "In the present study, we demonstrated that a peptide vaccine targeting Sema3E could suppress inflammation in visceral WAT and improve glucose intolerance in mice with dietary obesity." (PMID 30846754, 2019).
ovarian carcinoma (5 papers, 2011 to 2018). A malignant neoplasm originating from the surface ovarian epithelium. "The axon guidance molecule, Semaphorin-3E (Sema3E), has been identified in the past several years to be overexpressed in breast, colon, and ovarian cancers, and has also been shown to be associated with worse disease progression or metastatic cancer." (PMID 27911862, 2016). "Other studies showed Sema3E-dependent activation and nuclear translocation of the transcription factor Snail in ovarian cancer cells, or rather dependence-receptor features of PlexinD1 in breast cancer cells." (PMID 27749937, 2016). "In ovarian cancer cells it was reported that Sema3E signaling drives nuclear translocation of Snail, a transcription factor controlling E-cadherin expression." (PMID 27749937, 2016). "Notably, it was previously reported that the nuclear translocation of another transcription factor (Snail) induced by Sema3E in ovarian cancer cells was mediated by the PI3K/AKT pathway." (PMID 27749937, 2016).
airway hyperresponsiveness (4 papers, 2022 to 2025). "In the Sema3E treatment protocol, exogenous Sema3E was administrated intranasally before challenge in AS model to study the effect of Sema3E on airway hyperresponsiveness, airway inflammation, mucus production, and collagen deposition." (PMID 38111650, 2023).
glioblastoma (4 papers, 2012 to 2020). The most malignant astrocytic tumor (WHO grade IV). "For example SEMA3D and SEMA3E displayed strong inhibitory effect on the glioblastoma cells whereas SEMA3A and SEMA3B expression just caused persistent cell shape contraction." (PMID 25961819, 2015). "The same inhibitory effects on tumor growth were observed in a study of the overexpression of full-length uncleavable mutant Sema3E in glioblastoma cell lines, in vitro and in vivo." (PMID 27911862, 2016). "In another study, both SEMA3D and SEMA3E was found to inhibit glioblastoma cell growth." (PMID 32241267, 2020). "To determine the effects of sema3E and sema3D expression in glioblastoma cells on the survival of tumor bearing mice, we implanted control U87MG cells or cells expressing either sema3D or sema3E in the brain cortex of mice and monitored tumor development and mouse survival." (PMID 22936999, 2012). "Sema3D and sema3E displayed the strongest inhibitory effects and their expression in U373MG or in U87MG glioblastoma cells implanted in the brains of mice prolonged the survival of the mice by more then two folds." (PMID 22936999, 2012).
chronic asthma (3 papers, 2017 to 2025). An asthma that is characterized by the development of persistent airway inflammation and recurrent attacks of breathlessness and wheezing, which vary in severity and frequency. "Overall, the levels of IgG and IgE increased selectively in response to Sema3E deficiency, reflecting the unique immune niche in each chronic asthma model and emphasizing the homeostatic role of Sema3E in these contexts." (PMID 40512736, 2025). "Of great therapeutic importance, administration of extrinsic recombinant Sema3E, during or after development of the disease, alleviates chronic asthma facets." (PMID 29228740, 2017). "Hence, our data suggests that Sema3E selectively regulates cellular and molecular niches in both chronic asthma models." (PMID 40512736, 2025). "In addition, recent gene modification in mice allowed to identify for example the role of the potassium channels Kca3.1 in airway remodeling, and the regulatory role of semaphorin 3E (Sema3E) in inflammatory and remodeling responses in chronic asthma." (PMID 33101301, 2020).
gastric cancer (3 papers, 2015 to 2021). A primary or metastatic malignant neoplasm involving the stomach. "Upregulation of Sema3E in breast, colon, ovarian, and gastric cancer was associated with progressively worse or more invasive/metastatic cancer." (PMID 27911862, 2016). "Otherwise, we found that Sema3E inhibited the migration and invasion of gastric cancer cells, which were associated with up-regulation of E-Cadherin and reduction of ERK1/2 and Akt phosphorylation." (PMID 26036259, 2015). "Sema3E overexpression inhibited migration and invasion of gastric cancer cells, which was associated with induction of E-cadherin and reduction of Akt and ERK1/2 phosphorylation." (PMID 26036259, 2015). "Sema3E overexpression alone restricted the proliferation of gastric cancer cell lines, which may be caused by a delayed entry into S phase during cell cycle progression; it may also be caused by the promotion of apoptosis as well as a decrease in ERK1/2 and Akt phosphorylation." (PMID 26036259, 2015). "Sema3E overexpression in gastric cancer cell lines yielded the same result – reduced cell proliferation in vitro due to less G1 to S phase transition as well as promotion of apoptosis." (PMID 27911862, 2016). "A very recent study on gastric cancer has found that high Sema3E mRNA levels correlated with worse survival in human gastric cancer." (PMID 27911862, 2016). "As both p300 and Sema3E are inactivated in gastric cancer and p300 can promote gene transcription through its HAT activity, we sought to find a possible relationship between these two proteins." (PMID 26036259, 2015). "Together, the present evidence leads us to propose that it is the full-length Sema3E protein that participates in the inhibition of gastric cancer." (PMID 26036259, 2015). "Fortunately, we were able to demonstrate a positive correlation between Sema3E and p300 in gastric cancer." (PMID 26036259, 2015). "Immunohistochemical assay confirmed the substantially decreased expression of Sema3E in gastric cancer in 90/90 (100%) pairs of tissues." (PMID 26036259, 2015). "Quantitative real-time PCR of SEMA3E in a panel of 26 pairs of tissues agreed with the initial PCR result, and obvious down-regulation of SEMA3E mRNA was observed in 21/26 (80.77%) gastric cancer tissues when the cut-off was set as 1(P < 0.001)." (PMID 26036259, 2015). "In conclusion, our study provides evidence that silencing of Sema3E contributes to gastric cancer progression and metastasis." (PMID 26036259, 2015). "Together, the present evidence leads us to propose that up-regulation of E-cadherin and reverse of EMT contribute to Sema3E's inhibitory effect on gastric cancer cells invasion." (PMID 26036259, 2015). "The expression level of Sema3E was significantly and inversely correlated with tumor volume (P < 0.05), lymphatic invasion (P < 0.05) and gastric cancer progression (P < 0.001)." (PMID 26036259, 2015). "MRNA level of SEMA3E was significantly down-regulated in gastric cancer compared with corresponding adjacent normal tissues." (PMID 26036259, 2015). "Ectopic expression of Sema3E inhibited proliferation and colony formation of gastric cancer cell lines in vitro and xenografts in vivo." (PMID 26036259, 2015). "The results indicated that Sema3E could appreciably suppress the proliferation of gastric cancer cells." (PMID 26036259, 2015). "As a novel finding, down-regulation of Sema3E in gastric cancer may result from reduction of p300 and up-regulation of class I HDAC." (PMID 26036259, 2015). "In addition, the level of Sema3E decreased gradually with gastric cancer progression, and in TNM III and IV gastric cancer tissues Sema3E protein was barely detectable (P < 0.001)." (PMID 26036259, 2015). "We suggest that silencing of Sema3E contributes to the pathogenesis of gastric cancer." (PMID 26036259, 2015). "Twist overexpression abolished Sema3E's inhibitory effect on gastric cancer cells invasion." (PMID 26036259, 2015).
gastric cancer (continued). "We found that Sema3E was significantly decreased in gastric cancer." (PMID 26036259, 2015). "Our study is the first to describe the expression of Sema3E as well as the epigenetic mechanism involved in the deregulation of Sema3E in gastric cancer and the functional consequences of Sema3E overexpression on the proliferation, migration and invasiveness of gastric cancer cell lines." (PMID 26036259, 2015). "Both in vitro and in vivo experiments demonstrated that Sema3E could inhibit the proliferation of gastric cancer cell lines, which was achieved by inhibition of entry into S phase during cell cycle progression and by promotion of apoptosis." (PMID 26036259, 2015). "Additionally, Sema3E likely enhanced apoptosis of gastric cancer cell lines via induction of Bax and Bcl-xl." (PMID 26036259, 2015). "Our work has revealed that class I HDAC regulated SEMA3E transcription and may be involved in Sema3E down-regulation in gastric cancer; however, as for which HDAC is responsible for these effects requires further investigation." (PMID 26036259, 2015). "In this study, we provide evidence of frequent down-regulation of Sema3E in gastric cancer." (PMID 26036259, 2015). "First, the expression of Sema3E was evaluated in gastric cancer." (PMID 26036259, 2015). "Here, we demonstrated that Sema3E was decreased in gastric cancer." (PMID 26036259, 2015). "The expression and function of Sema3E in gastric cancer are currently unknown, and the mechanism that leads to the abnormal expression of Sema3E in cancers has not yet been documented." (PMID 26036259, 2015). "Abnormal expression of p300 and class I HDAC in gastric cancer may contribute to Sema3E silencing." (PMID 26036259, 2015). "In addition, adhesion-dependent colony formation assay further validated the ability of Sema3E to inhibit the proliferation of gastric cancer cells, as ectopic SEMA3E-transfected gastric cancer cells displayed a decrease in the number of colonies and smaller colony size." (PMID 26036259, 2015). "Sema3E was found to inhibit the phosphorylation of ERK1/2 and Akt in gastric cancer cell lines, which resulted in the inhibition of proliferation, migration and invasion." (PMID 26036259, 2015). "Furthermore, Sema3E could suppress the migration and invasion of gastric cancer cells in vitro." (PMID 26036259, 2015). "We checked the expression of SEMA3E in databases of COSMIC, ICGC and TCGA that contain microarray or deep sequencing data using gastric cancer samples." (PMID 26036259, 2015). "To investigate whether Sema3E participates in gastric cancer migration and invasion in vitro, we employed transwells without or with matrigel to assess the effects of Sema3E on cell migration and invasion respectively." (PMID 26036259, 2015).
ischemic stroke (3 papers, 2022). A stroke disorder caused by obstruction of blood flow to the brain, due to thrombotic (local blood clot formation) or embolic (due to a blood clot or other material traveling from another site) event. "The underlying mechanism of Sema3E/Plexin-D1 signaling involvement in functional brain recovery after ischemic stroke is unclear." (PMID 33978913, 2022). "This study demonstrated that the reactivation of Sema3E-Plexin-D1 signaling following ischemic stroke is essential for reconstructing a healthy vasculature via the regulation of VEGF signaling during vascular remodeling." (PMID 33978913, 2022). "The present study demonstrates that reactivation of Sema3E-Plexin-D1 signaling after ischemic stroke is critical for the re-establishment of healthy vasculature through modulation of VEGF signaling during vascular remodeling." (PMID 36091595, 2022). "Therefore, Sema3E negatively regulates vascular permeability, inducing NVU damage, and inhibiting Sema3E signaling is a novel therapeutic strategy for ischemic stroke." (PMID 35350431, 2022). "Because Sema3E-Plexin-D1 signaling is actively involved in many angiogenic conditions, we speculated that this signaling contributes to vascular remodeling after brain damage, such as in ischemic stroke." (PMID 33978913, 2022). "Furthermore, Sema3E/PlexinD1 signaling inhibits postischemic angiogenesis by regulating endothelial DLL4 and filopodia formation in a rat model of ischemic stroke." (PMID 36091595, 2022).
ovarian endometrioid carcinoma (3 papers, 2011 to 2025). "Here, we demonstrated a strong association between Sema3E expression and high-grade human ovarian endometrioid carcinoma." (PMID 21559368, 2011). "Sema3E/Plexin D1 promotes increased migratory and invasive potential and metastatic growth of ovarian endometrioid carcinoma cells." (PMID 26356073, 2015). "Consistent with this idea, we show that the cellular EMT induced by Sema3E/Plexin-D1 in ovarian endometrioid carcinoma cells occurs at least partially through PI3K and ERK/MAPK mediated nuclear translocation of Snail1." (PMID 21559368, 2011). "Among these 40 tumor samples, 25 were diagnosed as high-grade ovarian endometrioid carcinoma, and in all cases a significant level of Sema3E protein and transcript was detected." (PMID 21559368, 2011). "Taken together, our data provide evidence suggesting that PI3K and ERK/MAPK signaling pathways are involved in Sema3E/Plexin-D1-mediated EMT in ovarian endometrioid carcinomas." (PMID 21559368, 2011). "Based on preliminary immuno-screening results, we investigated in detail the expression of Sema3E and its receptors, Plexin-D1 and Neuropilin-1 (Npn1), in human ovarian endometrioid carcinomas." (PMID 21559368, 2011). "By contrast, most cases with low-grade ovarian endometrioid carcinoma exhibited barely detectable Sema3E levels." (PMID 21559368, 2011). "Using a human ovarian endometrioid carcinoma cell line and derived sublines with different invasive/migratory capabilities, we investigated the interrelation of Sema3E molecular and cellular signaling mechanisms and tumor invasiveness." (PMID 21559368, 2011). "Sema3E-induced EMT in ovarian endometrioid cancer cells was dependent on nuclear localization of Snail1 through activation of phosphatidylinositol-3-kinase and ERK/MAPK." (PMID 21559368, 2011). "High levels of Sema3E are found in high-grade ovarian endometrioid carcinoma." (PMID 26356073, 2015). "Collectively, these studies indicate that Sema3E/Plexin-D1 signaling in ovarian endometrioid cancer cells could regulate Snail1 translocation to the nucleus in order to induce EMT and concomitantly augment cell motility." (PMID 21559368, 2011). "This suggests Sema3E expression in ovarian endometrioid cancer cells could be involved in the acquisition of cellular invasive/migratory ability." (PMID 21559368, 2011). "Why is Sema3E-mediated EMT so specific to high-grade ovarian endometrioid carcinoma but not other ovarian epithelial tumors?" (PMID 21559368, 2011). "Here, we report that an axon guidance molecule, Sema3E, is highly expressed in human high-grade ovarian endometrioid carcinoma, but not low-grade or other ovarian epithelial tumors, and facilitates tumor progression." (PMID 21559368, 2011). "Furthermore, Sema3E/Plexin D1 induces EMT through nuclear localization of Snail and PI3K and ERK/MAPK signaling pathways, which play an important role in the Sema3E/Plexin D1-mediated EMT process in ovarian endometrioid carcinoma cells." (PMID 26356073, 2015). "Moreover, Sema3E was specifically over-expressed in high-grade ovarian endometrioid carcinoma in that other types of ovarian epithelial tumors including serous, mucinous and clear cell tumors, low-grade and high-grade alike, did not express Sema3E." (PMID 21559368, 2011).